MAF (MAF bZIP transcription factor)
Description:
Acts as a transcriptional activator or repressor. Involved in embryonic lens fiber cell development. Recruits the transcriptional coactivators CREBBP and/or EP300 to crystallin promoters leading to up-regulation of crystallin gene during lens fiber cell differentiation. Activates the expression of IL4 in T helper 2 (Th2) cells. Increases T-cell susceptibility to apoptosis by interacting with MYB and decreasing BCL2 expression. Together with PAX6, transactivates strongly the glucagon gene promoter through the G1 element. Activates transcription of the CD13 proximal promoter in endothelial cells. Represses transcription of the CD13 promoter in early stages of myelopoiesis by affecting the ETS1 and MYB cooperative interaction. Involved in the initial chondrocyte terminal differentiation and the disappearance of hypertrophic chondrocytes during endochondral bone development. Binds to the sequence 5'-[GT]G[GC]N[GT]NCTCAGNN-3' in the L7 promoter. Binds to the T-MARE (Maf response element) sites of lens-specific alpha- and beta-crystallin gene promoters. Binds element G1 on the glucagon promoter. Binds an AT-rich region adjacent to the TGC motif (atypical Maf response element) in the CD13 proximal promoter in endothelial cells (By similarity). When overexpressed, represses anti-oxidant response element (ARE)-mediated transcription. Involved either as an oncogene or as a tumor suppressor, depending on the cell context. Binds to the ARE sites of detoxifying enzyme gene promoters.
Synonyms: c-MAF; AYGRP; CCA4; CTRCT21
Tractability: PROTAC: UniProt records ubiquitination sites on it; ubiquitination databases record sites on it.
Gene: Protein-coding gene on chromosome 16 (79,585,843 to 79,600,737, reverse strand). Ensembl gene ENSG00000178573.
Subcellular location: Nucleus
Subcellular location (Human Protein Atlas): Nuclear bodies; Nucleoplasm; Golgi apparatus; Vesicles
Pathways (Reactome):
Developmental Biology: Differentiation of naive CD4+ T cells to T helper 2 cells (Th2 cells)
Gene expression (Transcription): RUNX2 regulates osteoblast differentiation
Gene Ontology:
Molecular function: identical protein binding; protein binding; sequence-specific double-stranded DNA binding; DNA-binding transcription factor activity, RNA polymerase II-specific; RNA polymerase II cis-regulatory region sequence-specific DNA binding; DNA binding; DNA-binding transcription activator activity, RNA polymerase II-specific; DNA-binding transcription factor activity; sequence-specific DNA binding
Biological process: megakaryocyte differentiation; integrated stress response signaling; lens fiber cell differentiation; negative regulation of transcription by RNA polymerase II; regulation of transcription by RNA polymerase II; transcription by RNA polymerase II; positive regulation of transcription by RNA polymerase II; regulation of DNA-templated transcription
Cellular component: RNA polymerase II transcription regulator complex; chromatin; nucleus; cytoplasm
Genetic constraint (gnomAD): Loss-of-function variants: 11 observed, 21.37 expected, observed/expected ratio (o/e) 0.51, 90% interval 0.32 to 0.85. The synonymous counts are far from expectation, so gnomAD's model fits this gene poorly and the ratio says little. Missense variants: 526 observed, 510.35 expected, observed/expected ratio (o/e) 1.03, 90% interval 0.96 to 1.11. Synonymous variants: 325 observed, 237.28 expected, observed/expected ratio (o/e) 1.37, 90% interval 1.25 to 1.5.
Homologues: Orthologues: chimpanzee MAF (99% identical), macaque MAF (99% identical), pig MAF (92% identical), dog MAF (91% identical), rat Maf (91% identical), mouse Maf (90% identical), zebrafish mafb (71% identical), tropical clawed frog maf (70% identical), zebrafish mafa (67% identical), Drosophila melanogaster tj (31% identical), Caenorhabditis elegans maf-1 (14% identical), Drosophila melanogaster maf-S (12% identical). Paralogues in human: MAFB (48% identical), MAFA (47% identical), NRL (33% identical), MAFK (18% identical), MAFG (17% identical), MAFF (17% identical).
Diseases named in the same sentence as MAF in open-access papers:
MAF is named in the same sentence as 121 diseases in open-access papers, as found by Europe PMC text mining. Sharing a sentence is not in itself a finding about the gene and the disease. The quoted sentences say what the papers report.
myeloma (50 papers, 2007 to 2025). "MAF encodes a transcription factor with a well-described oncogenic function in hematological malignancies, and has been shown to be a recurrent target for translocations and/or overexpression with potential consequences on the cell-cycle, proliferation and multiple myeloma growth." (PMID 34356658, 2021). "Through similar methods, the herbal acevaltrate and anti-bacterial/anti-viral nanchangmycin have been identified to inhibit OTUB1/c-MAF axis and induce myeloma cell apoptosis." (PMID 38264570, 2023). "GSK3β mediated c-MAF-phosphorylation and subsequent degradation through the ubiquitin-proteasome pathway in multiple myeloma." (PMID 35359922, 2022). "Some studies reported that MEK inhibition induces apoptosis of MAF-expressing myelomas and blocks survival signals provided by the microenvironment." (PMID 33562668, 2021). "For example, overexpression of MAF is a frequent oncogenic event in multiple myeloma, triggering pathological bone marrow stromal cell interactions and promoting proliferation." (PMID 34356658, 2021). "MAF overexpression is a frequent oncogenic event in multiple myeloma, stimulating cell cycle progression and altering bone marrow stromal interactions." (PMID 29089486, 2017). "Vk*myc, XBP-1 and c-MAF transgenic mice have been shown to develop myeloma-like malignancy, with localization of disease to bone marrow plus osteolysis." (PMID 23437401, 2013). "MAF transcription factors were originally identified as oncogenes and chromosomal translocation events in multiple myelomas frequently lead to the over-expression of c-MAF and MAFB." (PMID 19303416, 2009). "Elevated expression of NUAK1 in Multiple Myeloma was shown to be induced by members of the large MAF transcription factor family, which are homologous to the avian retroviral oncogene v-Maf, and two functional MAF response elements were identified in the NUAK1 promoter region." (PMID 38939918, 2024). "Additionally, the most activated TFs in each subgroup within the M1-M5 modules were identified as follows: MAF in the C0 IGLL5+ Myeloma Cells subgroup, LEF1 in the C1 IGHG4+ Myeloma Cells subgroup, TCF12 in the C2 MALAT1+ Myeloma Cells subgroup, and CREB5 in the C3 IGHG1+ Myeloma Cells subgroup." (PMID 39281682, 2024). "The protein expression of MAF, MAFB, and ARK5 was analyzed in nine human myeloma cell lines: Sachi, KM5, L363, JJN3, KMS-11, RPMI-8226, FR4, NOP-1, and KMS-12." (PMID 38282096, 2024). "In this study, we found SEs driving known oncogenes (ST3GAL6 and ADM) as w critical subtype-specific drivers (MAF and NUAK1) in myeloma pathogenesis." (PMID 33579893, 2021). "For instance nicotine induced MAF is a B-ZIP transcription factor and MAF translocation or overexpression has been observed in human multiple myeloma." (PMID 25401222, 2014). "The key myeloma-initiating genetic events are hyperdiploidy and translocations involving the immunoglobulin heavy chain (IgH) enhancer on chromosome 14, which leads to the activation of oncogenes (e.g., CCND1, CCND3, MAF, and MMSET)." (PMID 35982976, 2022). "Multiple myeloma is an incurable plasma cell malignancy, which is characterized by recurrent chromosomal aberrations that drive the expression of established oncogenes such as MYC, Cyclin D1, FGFR3/MMSET and MAF/MAFB." (PMID 33494394, 2021). "The highest levels of expression are found in the genetic category of MM that is non-hyperdiploid and, more specifically, in those myelomas that contain translocations between the IgH and MAF or cyclin D1 genes with dysregulated MAF or cyclin D-1 levels." (PMID 25568666, 2014). "Importantly, the MAF/SE/MAGI2 regulatory circuit could potentially represent an attractive therapeutic target for future regenerative and cell-based myeloma therapies." (PMID 33579893, 2021). "The data also rules out abnormalities involving MAF, MAFB, MYC or NSD2/FGFR3, which are chromosomal translocations clinically relevant for multiple myeloma diagnosis." (PMID 40027317, 2024).
myeloma (continued). "Through a multi-layer -omics approach, c-MAF was suggested to interact with IRF4 in normal and myeloma plasma cells although no experimental data supported this idea." (PMID 35359922, 2022).
breast carcinoma (13 papers, 2013 to 2024). "In fact, FOLR2 exhibits the highest level of correlation with MAF expression in breast carcinoma, a finding that agrees with the considerable decrease in FOLR2 expression that is seen upon MAF knockdown in human macrophages." (PMID 32532019, 2020). "Furthermore, we constructed a breast cancer in situ transplantation model using MDA-MB-453 (EGFP marker) to verify the Role of CHI3L1/MAF in promoting TNBC stemness and participating in immunosuppression by exogenously administering hrCHI3L1 or/and sh-MAF-1." (PMID 37838657, 2023). "Previously published studies have indicated that antimetastatic effects of Zol correlate with that tumour cell expression of the transcription factor MAF, whereas other studies have shown that high expression of GIPC1 and CAPG is associated with antitumour activity of Zol in breast cancer patients." (PMID 34733240, 2021). "DOCK4 may therefore be a component of a protein panel that responds to elevated c‐MAF expression within bone‐homing breast cancer cells." (PMID 30426503, 2019). "A recently completed clinical trial, named AZURE trial, postulated certain beneficial antitumor activity of bisphosphonates against breast cancer in the adjuvant setting in a subset of postmenopausal women who were negative for MAF transcription factor." (PMID 33670680, 2021). "However additionally, members of the ATF (activating transcription factor) and MAF (musculoaponeurotic fibrosarcoma) protein families have been shown to contribute to this complex and could thus be considered as potential additional biomarkers in breast cancer." (PMID 24073962, 2013).
colitis (13 papers, 2013 to 2025). Inflammation of the colon. "Furthermore, c-MAF overexpressing naïve CD4 T cells were unable to induce colitis as compared to WT controls." (PMID 29910812, 2018). "In our system this would mean that inactivation of MAF in these cells would limit the development of colitis, which is however not the case." (PMID 30992496, 2019). "However, c-MAF overexpression within memory/effector CD4 T cells, normally containing T regulatory cells, augmented colitis when co-transferred with naïve Th cells." (PMID 29910812, 2018).
fibrosarcoma (11 papers, 2008 to 2026). A malignant mesenchymal fibroblastic neoplasm affecting the soft tissue and bone. "Subsequently, the transcription regulator protein BACH1-transcription factor musculoaponeurotic fibrosarcoma (MAF) complex, which suppresses the expression of HO-1, is dissociated, releasing MAF, which binds with Nrf2 and induces HMOX1 transcription." (PMID 34452191, 2021). "The AP-1 transcription factor is a heterodimeric protein formed by c-fos, c-jun, activating transcription factor (ATF) and musculoaponeurotic fibrosarcoma (MAF) protein families." (PMID 23496845, 2013). "Predictive biomarkers beyond menopause are being sought and assessment of the transcription factor MAF (mesenchymal aponeurotic fibrosarcoma gene) appears to identify patients able to benefit from the addition of a bisphosphonate to standard adjuvant anticancer therapies." (PMID 35892899, 2022). "MAF encodes for nuclear transcriptional regulating proteins with a leucine zipper motif, and was identified in the genome of the acute transforming avian retrovirus AS42, which induces fibrosarcomas and has the ability to transform chicken embryo fibroblasts." (PMID 18992152, 2008).
lung cancer (8 papers, 2017 to 2025). A malignant neoplasm involving the lung. "In the absence of Fructosamine-3-kinase, NRF2 is glycated and binds to the small MAF proteins and increases the transactivation of its target genes in liver and lung cancer cells." (PMID 31884422, 2019).
COVID-19 (7 papers, 2020 to 2023). A disease caused by infection with severe acute respiratory syndrome coronavirus 2. "The link between the MAFB/MAF ratio and the gene profile of pathogenic macrophages in severe COVID-19 has also mechanistic implications." (PMID 33312178, 2020). "In fact, Enrichr analysis on the COVID-19 gene sets supported the association between MAFB- and MAF-dependent genes and COVID-19." (PMID 33312178, 2020). "As a whole, we propose that a high MAFB/MAF expression ratio in lung macrophages could serve as an accurate diagnostic tool for COVID-19 progression." (PMID 33312178, 2020). "Next, analysis of the genes differentially regulated by MAFB and MAF on the disease-associated database DisGeNet using the clusterProfiler tool revealed a very significant enrichment of several terms related to respiratory deterioration (a firmly established symptom of COVID-19)." (PMID 33312178, 2020). "For Mon IFI30, we also found MAFB and MAF as highly expressed and previous studies proposed their role for control of macrophage checkpoints in COVID-19 severity and as a marker for progression." (PMID 36230912, 2022). "Regarding the “HALLMARK_INFLAMMATORY_RESPONSE” gene set, MAFB and MAF were found to oppositely regulate the expression of a cluster of chemokine-encoding genes (CXCL10, CCL2, CCL7, CXCL9) that are associated to the COVID-19 “cytokine storm”." (PMID 33312178, 2020). "Solid evidences are presented that link overexpression of MAFB and silencing of MAF expression with clinical and biological features of severe COVID-19." (PMID 33312178, 2020). "Consequently, we hypothesize that MAFB and MAF shape the transcriptome of the fibrotic SPP1high and inflammatory monocyte-derived FCN1high pulmonary macrophage subsets, respectively, which exert a pathogenic role in severe COVID-19." (PMID 33312178, 2020). "On the other hand, the possibility of altering the MAFB/MAF ratio as a potential therapy for severe COVID-19 raises the question of the appropriate timing for such an approach." (PMID 33312178, 2020). "The altered MAFB/MAF expression ratio that we have found might have prognostic value in COVID-19 severity and progression, as well as potential therapeutic implications." (PMID 33312178, 2020). "Based on these hallmarks, and considering the pivotal role of macrophages in COVID-19 pathogenesis, we hypothesize that the transcription factors MAFB and MAF critically contribute to COVID-19 progression by shaping the response of macrophages to SARS-CoV-2." (PMID 33312178, 2020). "On the prognosis issue, an immediate consequence of our hypothesis would be that the genes positively regulated by MAFB or negatively regulated by MAF could be prognostic biomarkers for severe COVID-19." (PMID 33312178, 2020). "Therefore, considering the link between MAFB/MAF ratio and AHR expression, the proposed involvement of AhR in COVID-19 pathogenesis is well in agreement with our hypothesis on the contribution of MAFB and MAF to severe COVID-19." (PMID 33312178, 2020). "Altogether, these analyses strongly suggest a link between MAF/MAFB-regulated genes and COVID-19 pathology." (PMID 33312178, 2020). "Further supporting our hypothesis, additional GSEA also revealed co-enrichment of genes positively regulated by MAFB and negatively regulated by MAF in bronchoalveolar lavage fluid cells in COVID-19 patients (data not shown)." (PMID 33312178, 2020). "Indeed, reversing the macrophage MAFB/MAF expression ratio might impair the exacerbated inflammatory and profibrotic responses, and restore the defective IFN type I production, thus becoming a potential strategy to limit severity of COVID-19." (PMID 33312178, 2020).
diabetes (7 papers, 2021 to 2025). "While these two studies suggested a requirement for c-MAF in organ injury, we report a protective effect of c-MAF deficiency against diabetes and diabetes-induced nephropathy through c-MAF regulation of the glucose transporters SGLT2 and GLUT2, which are expressed in the proximal tubules of kidneys." (PMID 37895232, 2023). "We delved deeper into the specifics of MAM protein-protein interactions and discovered key connections between many of the altered MAM proteins in diabetes with several major protein regulators of inflammation, diabetes, and/or DR, specifically IL-1β, NFκBIA, FOXO1, SYVN1, STAT4, MAF, and LGALS3." (PMID 36139394, 2022).
lupus (7 papers, 2022 to 2025). "The dysregulation of the IL-21-TET2-AIM2-c-MAF pathway is a characteristic feature of lupus pathogenesis." (PMID 37638029, 2023). "Except for human findings, a previous study has suggested that murphy roths large/lymphoproliferative (MRL/lpr) lupus mice experienced reduced autoantibody levels and ameliorated clinical symptoms by impairing c‐MAF regulation in TFH cells after dexamethasone treatment." (PMID 35343082, 2022). "Our results have identified a role of AIM2 in promoting the TFH cell response and further revealed that the IL‐21‐TET2‐AIM2‐c‐MAF signalling pathway is dysregulated in lupus pathogenesis, which provides a potential therapeutic target for SLE." (PMID 35343082, 2022). "Here, our findings demonstrated that high AIM2 expression upregulates the TFH cell response and that the IL‐21‐AIM2‐TET2‐c‐MAF pathway contributes to autoimmune progression during lupus development, which may facilitate new clinical therapeutics targeting AIM2 in T cells for the treatment of SLE." (PMID 35343082, 2022). "In the context of T follicular helper (TFH) cell-mediated systemic lupus erythematosus (SLE), AIM2 was found to promote TFH cell differentiation and IL-21 production via the c-myofascial fibrosarcoma (c-MAF) signaling pathway." (PMID 39600708, 2024).
melanoma (7 papers, 2020 to 2025). A malignant, usually aggressive tumor composed of atypical, neoplastic melanocytes. "Next, we tested the effectiveness of the fibroblast‐derived ECMs generated from HDF, FRC, or MAF to protect BRAFV600E‐mutated melanoma cells against the anti‐proliferative effect of MAPK pathway inhibition." (PMID 34957688, 2022). "We show that DDR knockdown or the inhibition of their catalytic activity impairs drug tolerance that is promoted by MAF‐ or FRC‐derived ECM and induces melanoma cell death." (PMID 34957688, 2022). "IL‐6 and TGF‐β have been identified as the primary activators of MAF on CD8+ T cells, contributing to the suppression of melanoma microenvironment." (PMID 32931642, 2020). "The expression of MAF in antitumor CD8+ T cells contributes to their polarization toward a depleted phenotype, and TGF-β and IL-6 are able to induce MAF expression in CD8+ T cells in vitro and in vivo, while tumor-specific CD8+ T cells lacking MAF tend to eliminate melanoma cells." (PMID 37762054, 2023).